LINC01418 (long independently transcribed non-coding RNA 1418)
Synonyms: AC104041.1
Gene: Long non-coding RNA gene on chromosome 15 (81,610,828 to 82,013,579, reverse strand). Ensembl gene ENSG00000259692.
Diseases named in the same sentence as LINC01418 in open-access papers:
LINC01418 is named in the same sentence as 1 disease in open-access papers, as found by Europe PMC text mining. Sharing a sentence is not in itself a finding about the gene and the disease.
LINC01418 shares sentences with these, for which no sentence is quoted: cancer (1 paper).